RETN (resistin)
Diseases named in the same sentence as RETN in open-access papers (continued):
Sharing a sentence is not in itself a finding about the gene and the disease.
Obesity (continued). "We found significant negative correlations between serum resistin and age, BMI, total cholesterol, and HbA1c, suggesting a relationship with obesity, hypercholesterolemia, and poor glucose control." (PMID 41417360, 2025). "In this homogenous Mexican-American cohort, circulating resistin levels were not significantly different between groups with varying metabolic health or obesity statuses." (PMID 40362681, 2025). "More specifically, in studies of young, non-diabetic adults and children with obesity, resistin levels were higher than those of a control group." (PMID 39519480, 2024). "In addition, resistin correlated positively with indices of obesity, such as BMI, BMI z-score, TMI, HC, WHtR and leptin, while changes in resistin concentrations correlated positively with WC, WC z score, WHtR, muscle mass percentage and fat-free mass." (PMID 39519480, 2024). "Adipokines mainly involved in obesity and MetS are leptin, nonesterified free fatty acids, reactive oxygen species, adipocytic angiotensinogen, and resistin." (PMID 39411599, 2024). "The levels of determined hormones in the adipose tissue of animals from the palatable + KSK-94 group, such as leptin and resistin, after treatment, were at a comparable level as in the adipose tissue collected from the control group without obesity." (PMID 39065709, 2024). "Our findings indicate that 12 weeks of HIFT supplemented with spinach-derived thylakoid reduced levels of leptin, resistin, vaspin, visfatin, apelin, RBP4, chemrin, semaphorin3c and insulin resistance while increasing adiponectin and omentin levels in men with obesity." (PMID 37576981, 2023). "Although resistin appears as a significant link between obesity and T2D, it has no significant role in regulating bone metabolism." (PMID 36831180, 2023). "The results of this study indicate that SW20.1 may prevent obesity and its related metabolic syndrome by inducing ATF3 expression and inhibiting the crucial upstream resistin-related pathway." (PMID 37371606, 2023). "In our study, we observed higher IL1B and RETN mRNA in VAT of patients with obesity plus T2DM, rather than in obese patients with a euglycemic state." (PMID 38139276, 2023). "The following part of the review describes the key roles of adiponectin, leptin, resistin, IL-6, MCP-1 and PAI-1 recognized to be involved in the physiopathology of obesity and cited as relevant targets for limiting metabolic and vascular complications in obesity." (PMID 38136564, 2023). "Herein, resistin was elevated in children with overweight/obesity, both with and without MetS; however, the only significant difference was between children with MetS and those with normal body weight." (PMID 36920931, 2023). "Indeed, our results showed increased levels of plasma resistin in T2D-PDT patients and a positive correlation between resistin levels and BMI when considering all data, suggesting that increased resistin levels observed in T2D-PDT may be associated with obesity and/or metabolic syndrome." (PMID 36829785, 2023). "Secondly, the expression of TNF-α and resistin increased in patients with SO compared to patients with normal body composition, with obesity and without sarcopenia, and with sarcopenia only." (PMID 37853348, 2023). "Four cross-sectional studies show that third-trimester resistin concentrations do not differ between women with overweight or obesity and normal-weight women." (PMID 37834125, 2023). "In fact, fat cells are known to physiologically secrete hormones (leptin, adiponectin and resistin) and pro-inflammatory cytokines including IL-6 and TNF-α, which are recognized to be elevated during obesity, and in turn stimulate the recruitment of immune cell infiltrates." (PMID 37283765, 2023). "Paralleling this remodeling of adipose tissue, we found that leptin, resistin, glucagon-like peptide-1 (GLP-1), glucagon, TNF-α, and IL-6 were elevated in serum from DIO-HFD mice relative to CON-LFD, and DIO-VSG suppressed this obesity-driven increase." (PMID 37698918, 2023).
Obesity (continued). "The main objective of this study was to verify the effects of weight loss induced by RYGB on the circulating levels of systemic inflammatory markers adiponectin, resistin, leptin, TNF-alpha, IL1-beta interleukins, IL-6, IL-8, IL-17, IL-23 and IGF-1 in women with severe obesity and MS." (PMID 36788619, 2023). "The frequency of cells expressing CD14+CD95+ (45.8 ± 16.5) was higher in cells not treated with resistin in the colostrum from diabetic mothers with obesity." (PMID 36289594, 2022). "With obesity, greater secretion of pro-inflammatory adipokines (including leptin, IL-6, TNF-α, and resistin) was observed, affecting satiety and lipid metabolism, along with a decrease in anti-inflammatory and insulin-sensitizing cytokines such as adiponectin and IL-10." (PMID 36364915, 2022). "Resitin treatment did not alter the phagocytosis index of colostrum cells from mothers with diabetes and obesity (without 64 ± 8.2 and 69.2 ± 9.2 with resistin)." (PMID 36289594, 2022). "In both obesity and type 1 diabetes, leptin, resistin, and β-cell autoimmunity are elevated, but it is not clear yet if obesity accelerates or causes type 1 diabetes." (PMID 36147568, 2022). "Unlike other adipose-derived hormones like leptin and resistin, which correlate positively with obesity measures, adiponectin correlates inversely with obesity in rodents and humans." (PMID 35664415, 2022). "The frequencies of CD14+ cells and cells expressing CD95+, independent of resistin treatment, were higher in the colostrum from diabetic mothers with obesity." (PMID 36289594, 2022). "The resistin concentration in the colostrum was higher in diabetic mothers with obesity (375.3 ± 120.2) than in normal weight non-diabetic mothers (141.1 ± 63.9)." (PMID 36289594, 2022). "The frequency of cells expressing CD14+CD95+ was higher in cells not treated with resistin in the colostrum from diabetic mothers with obesity." (PMID 36289594, 2022). "The colostrum cells from diabetic mothers with obesity, irrespective of the presence of resistin, presented an increase in the apoptosis index (34.0 ± 6.5 without and 30.9 ± 6.0 with resistin) when compared with the normal weight group." (PMID 36289594, 2022). "Resistin, also known as ADSF (adipose tissue-specific secretory factor) or FIZZ3, (in inflammatory zone 3) is a novel adipokine that has been suggested to play an important role in obesity, insulin resistance and inflammation." (PMID 36097281, 2022). "The frequency of cells expressing CD14+, independent of resistin treatment, was higher in the colostrum from diabetic mothers with obesity (43.8 ± 19.2 and 41.8 ± 19.1 with and without, respectively)." (PMID 36289594, 2022). "Apoptosis, irrespective of the presence of resistin, increased, whereas microbicidal activity decreased in cells from diabetic mothers with obesity." (PMID 36289594, 2022). "Thus, along with IL-6, resistin, and TNF-α, leptin acts as an indicator of obesity initiation and insulin resistance." (PMID 36248900, 2022). "In conclusion, this meta-analysis suggested that resistin and follistatin levels, independent of obesity status, were higher in women with PCOS compared with those in healthy controls." (PMID 33740002, 2021). "Although the majority of studies confirm the correlation between resistin and obesity and Type 2 diabetes, not all studies show increases in resistin levels." (PMID 33679451, 2021). "Luminex analysis showed that in the HFD-induced obesity mouse model, there was an obvious increase in serum proinflammation cytokines such as TNF-α, MCP-1, IL-12, IL-1β, IL-6, CCL3, CXCL16, and Resistin, which were further alleviated significantly in the CD226KO group." (PMID 34823548, 2021). "Hence, a rise in body weight, blood glucose level, serum insulin, leptin and resistin levels along with reductions in serum adiponectin levels in HFD and sucrose fed rats indicates the development of obesity induced insulin resistance in them." (PMID 33917607, 2021).
Obesity (continued). "At the same time, it briefly describes the cancer-promoting mechanism of resistin, MIF and MCP-1 in obesity-related tumors, and finally summarizes the specific treatment opinions and measures for various adipokines and insulin/insulin-like growth factors in recent years." (PMID 34485124, 2021). "The inflammatory hormones leptin, PAI-1, and resistin were all reduced in the HF→LF group compared to both the HF and HF→HFB groups, indicating an improvement in the obese phenotype with the introduction of caloric restriction in established obesity." (PMID 33652785, 2021). "In contrast, in subjects with obesity, systemic levels of insulin, leptin, and resistin did not increase with gestational age, in line with reduced weight gain in this group." (PMID 34195568, 2021). "Thus, the aim of this study was to investigate the serum concentration of resistin in dogs with CBMT and its relationship with obesity, tumor aggressiveness, and survival." (PMID 32903534, 2020). "In the case of adiponectin (Acrp30), it has been found that their levels are low in psoriasis in correlation with obesity, but not in the case of leptin and resistin, which correlate with their exacerbation." (PMID 31275060, 2019). "Inflammation in obesity is manifested by increased circulating levels of classical pro-inflammatory cytokines, such as TNF and altered levels of adipokines, including leptin, resistin, and adiponectin." (PMID 31024226, 2019). "Several clinical and experimental studies have identified resistin as a key hormone linking insulin-resistance to obesity, notably through the activation of Toll Like Receptor (TLR) 4 signaling pathways." (PMID 30906281, 2019). "Some authors have reported positive correlations between resistin and markers of obesity and the MS in children, while others have not." (PMID 31404407, 2019). "Results from human studies addressing the level of resistin in obesity and T2D have varied, from showing an increase to no change." (PMID 30131766, 2018). "Some studies showed that resistin levels correlated with obesity and diabetes, while others failed to observe any correlation of resistin levels with metabolic markers." (PMID 29386698, 2017). "Our results suggest that the changes observed in the brain pathways activated by resistin and leptin can be observed without overt obesity." (PMID 29234283, 2017). "This 50 kDa adipokine was first discovered in a rat model when identifying genes that were differentially expressed during the development of obesity and type 2 diabetes; vaspin level is low in obesity and suppresses leptin, TNF-α, ICAM, and resistin synthesis." (PMID 28490838, 2017). "Furthermore, serum resistin and leptin have specific roles in the regulation of ATM in patients with modest obesity and early metabolic dysfunction." (PMID 27101398, 2016). "For instance, resistin, an adipokine mainly secreted from VAT, is elevated in obesity." (PMID 27148161, 2016). "One limitation of our study was that we were unable to verify the link between resistin and obesity due to a lack of BMI data." (PMID 27314854, 2016). "Scientific literature demonstrated that increased resistin levels in patients with psoriasis were independent of their obesity." (PMID 28097156, 2016). "This complex relationship between obesity and BMD could be explained by the effect on bone of a series of adipokines and cytokines secreted by adipose tissue, such as leptin, resistin, adiponectin, interleukin 6, and tumor necrosis factor-alpha." (PMID 27809297, 2016).
Obesity (continued). "Out of all pure adipokines, plasma levels of which were measured in the study; exclusively leptin, a marker of obesity, exhibited higher-than-normal values in both obese groups, while visfatin and resistin remained within the normal range (data not shown)." (PMID 26090072, 2015). "Although, the majority of studies confirm the correlation between resistin and obesity and Type 2 diabetes, a few reports show resistin was not increased in patients with severe insulin resistance and Type 2 diabetes." (PMID 26617526, 2015). "Early studies found that circulating resistin levels are elevated in genetic and DIO in mice and obese humans whereas other studies found that resistin is downregulated in human obesity and rodent obesity." (PMID 24109426, 2013). "In contrast the function of resistin in humans is not clear, as resistin levels in blood circulation are not correlated with obesity and insulin resistance." (PMID 23781214, 2013). "Our results do not support the role of resistin as an etiological link between obesity and diabetes." (PMID 23776497, 2013). "Some, but not other, authors found that plasma resistin levels positively correlate with obesity and other constituents of the metabolic syndrome." (PMID 22584415, 2012). "Resistin (RSTN) is an adipokine produced by mature adipocytes and macrophages, and it has been postulated that resistin might comprise the link between obesity and insulin resistance." (PMID 21686173, 2011). "In agreement with our data, resistin levels were stable after 2 days and 2 months of CPAP use in a group of subjects with OSA, suggesting that resistin is unlikely to play an important role in the insulin resistance or obesity seen in OSA." (PMID 21676224, 2011). "In non-critically ill patients, resistin was found to be related to impaired glucose tolerance, insulin resistance, metabolic syndrome, obesity and type 2 diabetes." (PMID 19545363, 2009). "The relationship between obesity and expression of resistin is not clear in humans, although the transcription of resistin mRNA is high in preadipocytes during differentiation." (PMID 18234104, 2008). "Like in rodents, the human homolog appears as an adipose-specific and obesity-regulated antagonist of insulin action or, conversely, blood/immune cells and not adipocytes are source of resistin." (PMID 17183659, 2006). "While it is apparent there are conflicting reports as to the role of serum resistin and its role in obesity mediated T2DM, no study to date has examined this in relation to a Saudi population with and without T2DM and/or CHD." (PMID 15998471, 2005). "Finally, resistin and GLP-1 levels were examined for their roles in obesity and insulin resistance." (PMID 40509530, 2025). "Additionally, we found negative correlations between resistin and obesity anthropometric parameters." (PMID 41011232, 2025). "Nevertheless, the same research also suggested that resistin might not be a key link between MetS and obesity, as resistin levels were not statistically different between groups of patients with T2DM and MetS." (PMID 39596980, 2024). "However, the results of other studies led to the conclusion that the serum resistin level is higher in asthmatics, regardless of comorbid obesity." (PMID 38542187, 2024). "In our study, serum levels of resistin were found to be significantly increased in the obese subjects (p < 0.0001) and in PCOS patients (p < 0.01) when compared with controls, whereas adiponectin was found to be significantly lower (p < 0.0001) in both obesity and PCOS." (PMID 39457645, 2024). "Interestingly, obesity does not affect the secretion of resistin in obese women with postmenopausal osteoporosis, however, combined aerobic and resistance exercises decrease resistin levels." (PMID 36831180, 2023). "Unlike the results in RBP4 and asprosin, obesity could independently or collectively act as an interfering factor in significantly upregulating the expression of leptin, nampt/visfatin and resistin." (PMID 38069063, 2023).
Obesity (continued). "However, the exact role of resistin in obesity and type 2 diabetes mellitus in humans have not been comprehensively defined." (PMID 38149100, 2023). "Since serum resistin levels were positively correlated to the central/visceral obesity (but not BMI) and IR, resistin may be involved in driving obesity-related HCC, though further investigations are needed." (PMID 37266440, 2023). "Interestingly, both leptin and another molecule, resistin correlate with other inflammatory markers of obesity, independent of BMI." (PMID 36788619, 2023). "Consistent with reduced obesity, HFD‐fed Cxxc5−/− mice exhibited markedly improved glucose tolerance and insulin sensitivity, with improved levels of metabolic parameters, including leptin, resistin, adiponectin, TGs, total cholesterol and HDL‐cholesterol levels." (PMID 35384342, 2022). "Moreover, the type of liver steatosis experimental model (from either nutritionally or genetic-induced obesity) did not affect the hepatic levels of the adipocytokines visfatin and resistin, observed in conditions of liver surgery." (PMID 35625715, 2022). "Moreover, the studies have shown that a decreased concentration of adiponectin and interleukin 10 and an increased concentration of leptin, resistin, interleukin 6, and MCP-1 could be a potential marker of obesity and its accompanying disorders." (PMID 34769133, 2021). "While the significance and even existence of resistin in human adipocytes has been contentious, by analysing conditioned medium from subcutaneous adipose tissue (SAT) from lean and obese humans, rather than isolated adipocytes, we recently found it to be secreted from SAT and increased with obesity." (PMID 33528828, 2021). "Recent evidence suggests that circulating resistin concentrations do not reflect the degree of obesity in humans, but it is related to some inflammatory diseases, such as chronic kidney disease, rheumatoid arthritis, coronary atherosclerosis, T2 diabetes mellitus, and sepsis." (PMID 35011183, 2021). "Circulating levels of resistin and follistatin, independent of obesity status, are higher in women with PCOS compared with controls, showing that these adipokines may contribute to the pathology of PCOS." (PMID 33740002, 2021). "In humans, resistin is predominantly produced by inflammatory cells, and resistin concentrations do not reflect the degree of obesity, although they may predict cardiovascular outcomes." (PMID 35011183, 2021). "However, the possible relationships between circulating resistin levels and insulin resistance in individuals affected by obesity with and without diabetes have not been clarified." (PMID 33192583, 2020). "Interestingly, resistin levels are also increased in the GCF of individuals with periodontal disease in the absence of obesity." (PMID 32410876, 2020). "In addition, sodium valproate could increase the expression of adipokines in the brain and pituitary (cephalokines), which regulates resistin and angiopoietin-like protein 4 (ANGPTL4) that might have a role in obesity and insulin resistance." (PMID 32952581, 2020). "Finally, our results also demonstrated increased resistin levels in obese children and in those with MS compared with control children, which is expected in obesity, as well as a negative correlation between irisin and resistin." (PMID 31404407, 2019). "Although visfatin serum levels were comparable between patients with or without type 2 diabetes or obesity, the authors observed a significant correlation between visfatin levels and biomarkers of liver and kidney dysfunction and other adipokines such as resistin and leptin." (PMID 31569348, 2019). "Western blots showed that the proinflammatory adipokine, resistin, is significantly increased in white adipose tissues (WAT) of the MHO mice, revealing our newly proposed, miR-155-suppressed “secondary wave inflammatory state (SWIS),” characteristic of MHO transition to classical obesity (CO)." (PMID 30369883, 2018).